IL17A (interleukin 17A)
Diseases named in the same sentence as IL17A in open-access papers (continued):
Sharing a sentence is not in itself a finding about the gene and the disease.
infection (continued). "We then assayed IL-17A in BALF 6 hours after infection in these animals and those that received an isotype control." (PMID 29813133, 2018). "In immunized mice, increase in immune cytokines (IL-12p70, IL-4, IL-5, and IL-17A) induced by SPY1 were further upregulated by P17 treatment, whereas the decrease in the infection-associated inflammatory cytokine TNF-α by SPY1 was reversed." (PMID 30116243, 2018). "Further, serum levels of interleukin (IL)-2, interferon γ, tumor necrosis factor (TNF)-α, IL-12p70, IL-22, IL-17A, and IL-5 increased significantly after infection." (PMID 30564216, 2018). "To determine the role of IL-17A in our protection studies, we quantified the levels of this cytokine in the nasal tissues of mice immunised with DacB, MetQ, or PnrA 3 days after infection." (PMID 30405609, 2018). "An important player for pro-inflammatory Th17 cells, IL-17A, significantly decreased due to the infection." (PMID 29760694, 2018). "After M. bovis 68002 infection, the responses of IP-10 and IL-17A (mRNA and protein) to PPD-B and CE showed kinetics similar to those of IFN-γ responses." (PMID 29560355, 2018). "Following infection with Campylobacter, the immune response in the cecal tissues appears to be more focused on the Th17 pathway featuring IL-6 induction with IL-17A and IL-17F responses, as compared to that observed in the ileum tissues." (PMID 29753324, 2018). "The only cell lineage that produced IL-17A under these conditions were γδ T cells, showing a rise in intracellular IL17A+ cells from 0.58% to 3.8% following infection." (PMID 29813133, 2018). "Here, we monitored that the nasal tissues of mice vaccinated with DacB, PnrA, and PspA showed significantly increased IL-17A levels 3 days after infection with pneumococci that correlated with protection." (PMID 30405609, 2018). "The percentages of IFN-γ-positive cells among the Vγ1+γδT and Vγ4+γδT subsets all increased significantly after infection, with similar rates of increase; this was different from the IL-17A production, which was mainly derived from Vγ4+γδT cells." (PMID 28912779, 2017). "We found that cag+ strain infection induced IL-17A secretion in mouse gastric tissues as well as spleen, while cag− infection did not." (PMID 28286572, 2017). "To analyze the role of IL-17A in resistance, we neutralized soluble IL-17A with anti-IL-17A mAb throughout the infection after challenge." (PMID 28542595, 2017). "We believe that studies in bronchoalveolar lavages would be required to elucidate if AA TB individuals, who secrete higher IL-17A levels, displayed increased neutrophils recruitment to the site of infection." (PMID 28098168, 2017). "Apart from that, IL-17A/F and TNFα can also have pathological effects, which is clearly true in the infection with R. typhi." (PMID 28770333, 2017). "Consistently, significantly higher concentrations of Th17-associated cytokines (including IL-17A and IL-6) were seen in lung homogenates from IRAK-M KO mice after smoke-induced exacerbations of LPS infection." (PMID 28951634, 2017). "ICS-assays revealed the presence of APP-CCE specific CD4+CD8αdim IL-17A-producing T cells in blood and lung tissue in most infected animals during the acute and chronic phase of infection and a minor fraction of these cells co-produced TNF-α." (PMID 28166835, 2017). "Prior literature has suggested an important role for IL-17A in the resolution of infection with the protozoan parasite T. cruzi." (PMID 28278264, 2017). "In antibiotic-treated mice there was significantly less intrapulmonary IL-17A produced in response to infection with K. pneumoniae or S. pneumoniae, compared to non-antibiotic-treated mice." (PMID 29142211, 2017). "γδT cells, especially the Vγ4+γδT subset, were the main source of IL-17A during the early phase of the infection." (PMID 28912779, 2017).
infection (continued). "We found that the deficiency of IL-6 or IL-23 impaired the IL-17A-production, which was ~2.5 times smaller than C57BL/6 mice at the same period of infection (p < 0.05)." (PMID 28871251, 2017). "Intrapulmonary GM-CSF production in response to infection is regulated by the microbiota via interleukin-17A (IL-17A)." (PMID 29142211, 2017). "Interleukin 17a was elevated by infection of rhinovirus in the lung, and led to upregulation of the Oas1g gene, which caused the degradation of viral RNAs." (PMID 29163367, 2017). "Increased pulmonary GM-CSF production in response to infection is primed by the microbiota through interleukin-17A." (PMID 29142211, 2017). "Our data suggest that IL-6-production by bone marrow-derived macrophages (BMDMs) is important to promote the IL-17A production and consequent induction of a protective immune response and granuloma formation during P. brasiliensis experimental infection." (PMID 28871251, 2017). "IL-17A promotes IFNγ-induced expression of iNOS and NO release in lung epithelial cells in vivo and acts protective in the infection with C. muridarum." (PMID 28222146, 2017). "Infection of primary fibroblasts resulted in lower plaque formation when fibroblasts were primed with IL-17A." (PMID 28895860, 2017). "To characterize the mechanism of differential IL-17A and IFNγ expression between WT and IL-1RI−/− lungs, we identified the main sources of these cytokines after C. neoformans 52D infection." (PMID 29403476, 2017). "By in vivo intracellular cytokine staining (ICS) we uncovered a cell population co-producing IL-23p19 and IL-17A in the lungs of C57Bl/6 mice within the first eight hours of infection with 5x107A." (PMID 28095479, 2017). "At d1 post-infection, IL-17a and IL-17f were upregulated 25,000 and 15,000-fold, respectively, compared to controls, and ≈20,000 and ≈1,500-fold compared to sterile bead-instilled animals." (PMID 28680858, 2017). "In the liver of mice infected with Listeria monocytogenes, γδT cells released a large amount of IL-17A within 1 h post-infection, which was significantly larger than the amount of IL-17A secreted by Th17 cells at the late stage of the infection." (PMID 28912779, 2017). "IL-17A+γδT cells were significantly increased after infection, but the major subsets of IL-17A-secreting γδT cells in severe influenza virus infection were unclear." (PMID 28912779, 2017). "All CD4+IFNγ-/- T cell recipients that received anti-IL-17A hardly lost weight upon R. typhi infection (left), showed a very weak temporary clinical score peaking on day 12 post infection (middle) and survived the infection (right)." (PMID 28222146, 2017). "Despite this evidence, the exact role of ILC3-derived IL-17F and its mechanisms of action in infection and disease, and how its effects differ from those of IL-17A, remain incompletely understood." (PMID 29085366, 2017). "Induction of IFN-I in macrophages by bacterial infection reduces IL-17A/F variant expression, followed by a decrease in IL-17A(+) γδ T cells, further highlighting the role of IFN-I on T cell populations during infection." (PMID 28428788, 2017). "Recent progress shows importance of IL17A in both innate and acquired immunity against infections, it is considered as an important inflammatory mediator that is critical in the protection from pneumococcal colonization in airways." (PMID 29021577, 2017). "By day 5 of infection, these mice also have fewer IL-17A+ γδ T cells, severe liver necrosis and a higher chance of fatality." (PMID 28824166, 2017). "There is some evidence that Th17-type cytokines (IL-17A and IL-23) contribute to protection against infection with wild-type (WT) C. neoformans; however, they appear to be less effective compared to Th1-type cytokines." (PMID 29403476, 2017). "The findings from prior studies have suggested a possible protective role of IL-17A in experimental infection models and in human ChD." (PMID 28278264, 2017).
infection (continued). "In this model, WT mice harbored an average of 99% fewer GAS in vaginal swabs after 3 weeks of infection compared to IL-17A−/− mice (1–5 × 105 CFU/swab versus 102–103 CFU/swab; p < 0.01)." (PMID 27241677, 2016). "TLR7/9-/- mice produce increased levels of IL6, TNF-α, and IL17A during Histoplasma infection, and similar results have been observed for the endemic fungal pathogen P. brasiliensis during infection of TLR9-/- mice." (PMID 27459510, 2016). "Taken together these findings indicate that IL-17A contributes to the innate immune defenses of the MG against infection by pyogenic bacteria." (PMID 27100324, 2016). "For example, it has been shown that infection of C57BL/6 mice with G. muris induces upregulation of interleukin 17A starting 1 week post-infection." (PMID 26973630, 2016). "For example, IL-17A was detected in higher levels in both the mutant-infected mice when compared to WT S. typhimurium-infected animals during early stages of infection." (PMID 27891321, 2016). "In H1N1 influenza virus-infected mice, significantly up-regulated IL-17A expression was detected in lung tissue as early as 2 days post-infection (dpi)." (PMID 26735852, 2016). "Draining lymph node cells from gp91phox−/− mice produced more IL-17A 8 weeks post-infection than cells from WT mice." (PMID 27056545, 2016). "The bacterial number in the liver and spleen of IL‐17A KO mice was also significantly higher on days 60 and 120 after the infection than those in the wild‐type C57BL/6 mice." (PMID 27980775, 2016). "Compared with naive animals, the level of IFNγ, IL-1β, IL-17A, and IL-12 was increased at 5 days post infection in PEC." (PMID 27721814, 2016). "In our study, examination of vaginal smears also revealed a significant increase in inflammation in WT Balb/c mice in the first week of infection, while infiltrates remained low in IL-17A−/− mice in the same period." (PMID 27241677, 2016). "In the case of infection with a low dose (1 × 103 cfu) of M. tuberculosis, all IL‐17A KO mice died by 1 year after the infection, whereas approximately 70% of the infected wild‐type C57BL/6 mice survived." (PMID 27980775, 2016). "Protected mice received an intranasal B. pertussis challenge 56 days after the primary infection (D0) and showed increased percentages of IFNγ- and IL-17A-producing Prn-specific CD4+ CD44+ T-cells on 10 days p.c. compared to the percentage in naive mice." (PMID 27711188, 2016). "Of particular importance, B-1a cell-derived natural antibodies can rescue Il17a-/- mice from otherwise lethal infections, indicating a critical role of IL-17A in regulating B-1a response against H1N1 infections." (PMID 26735852, 2016). "We first examined the survival rate of IL‐17A KO mice after intratracheal (i.t.)infection with M. tuberculosis." (PMID 27980775, 2016). "PD attenuated the vaccine-boosted IgG and IFN-γ responses to infection, but amplified the over-exuberant IL17A response driven by any S. Typhi exposure." (PMID 27467505, 2016). "IL-17-/- mice also showed a reduced parasite burden at the peak of infection, thus inferring a detrimental role for LRV1-dependent IL-17A and confirming the existence of a pathogenic TLR3-IL-17A signalling axis." (PMID 27658195, 2016). "On the other hand, IL‐17A‐producing TCR γδ+ T cells have been reported to participate in the immune response at an early stage of infection with Listeria monocytogenes and Mycobacterium bovis in mice." (PMID 27980775, 2016). "The differential response of IFN-γ, IL-17A and IL-10 has implications for how the two breeds fight infection but also how each breed controls inflammation." (PMID 27069644, 2016). "In the persistent estrus model in Balb/c mice infected with M1 GAS, IL-17A−/− mice also exhibited significantly lower levels of neutrophil and monocyte infiltration at 3 days post-infection (p = 0.0129 and 0.0276, respectively)." (PMID 27241677, 2016).
infection (continued). "Recently, many reports have suggested a broader and more complex role for IL‐17A in various infections." (PMID 27980775, 2016). "Cytokines typical of the immune response (IL-1β, IL-2, IFN-γ, IL-4, IL-17A) were analyzed at 2 and 28 days after infection." (PMID 27189736, 2016). "Overall, expression of IL-17A and IL-17F genes during infection raise the point of the contribution of these cytokines to the defence of the udder against bacterial infection." (PMID 26062913, 2015). "Both CD4+Foxp3− effector cells and CD4+Foxp3+ Tregs responded to infection by expressing IL-17A in the draining axillary lymph nodes (ALN), cervical lymph nodes (CLN) and MOIL in infected mice." (PMID 25790134, 2015). "The primary function for IL-17A in F. tularensis LVS infection is proposed to be induction of IL-12 and IFN-γ by dendritic cells and macrophages, thus driving the development of critical Th1 responses required for clearance of the pathogen." (PMID 26379269, 2015). "Consistent with the induction of IL-17A following infection, both of these genes were induced in isotype-treated mice after infection." (PMID 26213975, 2015). "Using a new cell line, called the PS cell line, which we characterized in details in terms of phenotypic markers and response to bacterial agonists, we analysed the influence of IL-17A on the innate immune response of MEC to infection by E. coli." (PMID 26062913, 2015). "From the data presented in this report, we can clearly conclude that expression of IL-17A and IL-17F genes is induced approx. 100-fold upon infection by E. coli." (PMID 26062913, 2015). "The production of IFN-γ, IL-17A and IL-22 by colonic LP cells was reduced in Ccr2−/− mice on day 12 post infection." (PMID 26269452, 2015). "We report that, neutralization of IL-17A in sublingually immunized IFN-γ-/- mice post-infection resulted in a significant (p < 0.001) increase in the bacterial load compared with sublingually immunized mice injected the isotype control IgG antibody." (PMID 26168305, 2015). "In case of L. monocytogenes infection, a large number of γδ T cells accumulate in the lymph organs shortly after infection and begin to produce IL17A, signifying the role of Tγδ17 cells in the Listeria infection." (PMID 25699053, 2015). "Consistent with recent reports in mice infected with C. neoformans H99 or the less virulent strains 52D or H99γ where some protective role for IL-17A was observed, we found that IL-17A induction by pICLC was partly responsible for control of the infection." (PMID 26252005, 2015). "Although a fraction of Tregs produced IL-17A on d1 and d2 after infection Tregs still increased IL-17A in effector cells, decreased fungal burden, and modulated immunopathology and weight loss in Treg recipients during OPC on d5 (data not shown,)." (PMID 25790134, 2015). "Neutrophils and macrophages have also been described as an important source of IL-17A in infection-induced allergic airways disease." (PMID 26201093, 2015). "IL-17 expression by TCRαβ+ or TCRγδ+ lymphocytes one day post-infection was recently demonstrated by means of a fate reporter mouse in which an eYFP reporter irreversibly marks all cells with a history of IL-17A promoter activity." (PMID 26274976, 2015). "With regard to the innate immune response to infection, IL-17A was found in milk cell RNA extracts in the early phase (8 hpc) of the inflammatory response as well as in milk leukocytes from cows suffering from S. aureus mastitis." (PMID 25948480, 2015). "These cells are characterized as producers of IL-17A, IL-17F, IL-21, and IL-22 and are involved in host defensive mechanisms to various infections, especially extracellular bacterial infections, but also in the pathogenesis of autoimmune diseases." (PMID 26525279, 2015). "Instead, we found that the SaeRS TCS plays a significant role in the production of not only IFN-γ but also IL-1β, IL-6, MIP-2, and IL-17A/F during murine infection." (PMID 26147796, 2015).
infection (continued). "Relationships between IL-17A levels and infection status, important clinical measures and subsequent Pseudomonas aeruginosa infection were determined." (PMID 25822228, 2015). "Cell sorting by flow cytometry suggested that ghrelin-treated IL-17A+ T cell number was significantly restored by Ad-S6K1 infection both in splenic total T cells and CD4+ T cells." (PMID 25658305, 2015). "The rapid production of IL17A was reported in the lungs at a very early stage after intravenous infection with C. albicans." (PMID 25699053, 2015). "In E. multilocularis lesions, IL-17A mRNA expression was increased at the very early stage of infection, by 6.9-fold at day 2 and by 9.6-fold at day 8 p.i., and decreased at the late stage, from day 180 to day 360 p.i.." (PMID 24637903, 2014). "Among these, γδ T cells have the inherent ability to very rapidly produce IL-17A as an essential component of the innate immune response, and γδ T-cell-derived IL-17A is one of the earliest sources of this cytokine after infection in mucosal tissues." (PMID 24408967, 2014). "Blocking of IL-17A or IL-1 resulted in a significant abrogation of neutrophil recruitment to the airways in the initial phase of infection or at the peak of viral replication, respectively." (PMID 24918427, 2014). "IL-17A was previously reported to inhibit immigration of NK and other cell types into the site of infection in AD skin and to promote WR replication, while IFNγ reveals immunomodulatory and antiviral properties." (PMID 25486419, 2014). "IL-4 is recognized as one of the most critical cytokines for mediating protective immunity to H. polygyrus; however, Ab-mediated depletion of IL-17A has recently been found to have little effect on the outcome of primary infection with this parasite." (PMID 25114104, 2014). "These lymphocytes are the major responding T cell subset in the lung of mice infected with F. Tularensis bacterium, releasing large amounts of IL-17a during the early stages of infection whereas CD4+ T cells start to produce this cytokine later." (PMID 25330249, 2014). "Conversely, treating mice with anti-IL-17A antibody during infection resulted in decreased survival." (PMID 25296161, 2014). "After infection with L. monocytogenes, mice of identical severity culled at 29 h were analysed for their splenic IL-17A mRNA expression." (PMID 24728387, 2014). "The expression of two genes (TAC1 and IL17A), which play major roles in inflammatory reactions, was remarkably up-regulated during the infection period." (PMID 24392094, 2014). "Whereas IL-17A supports protective immune responses during mycobacterial infections, the role of IL-22 after infection with Mycobacterium tuberculosis (Mtb) is yet poorly characterized." (PMID 23460846, 2013). "To confirm that local IL-17A enhances the early neutrophil infiltration in RSV-infected mice, we therefore neutralized IL-17A during the first days of infection using an IL-17A antibody." (PMID 24194936, 2013). "IL-17A acts as the main cytokine responsible for initiating innate responses against infection by stimulating the production of cytokines, neutrophil chemoattractants, and antimicrobial peptides." (PMID 23378722, 2013). "Recent findings show that ectopic lymph node formation in the lung upon infections requires IL-17A derived from CD4+ T cells." (PMID 23383714, 2013). "IFN-γ and IL-17a protein were detected at 24 hrs post-infection only in immunized and challenged mice (p<0.001 vs RV-adjuvant treatment)." (PMID 24086140, 2013). "In order to examine the role of IL-17A in bacterial clearance, we compared the course of infection in IL-17A-defective (IL-17A−/−) and WT mice." (PMID 23592988, 2013). "In the M. bovis-infected mouse model, the IL-17A secretion by γδT cells is essential for mature granuloma formation and resolution of infection." (PMID 23956759, 2013). "Splenocytes from the Sup ODN treated donors produced significantly more IL-17A than did those from infection-matched controls (p<0.05)." (PMID 23844143, 2013).